CD14 (CD14 molecule)
Diseases named in the same sentence as CD14 in open-access papers (continued):
Sharing a sentence is not in itself a finding about the gene and the disease.
infection (continued). "Infection of CD14+ monocytes with ORFV-S at MOIs 1 and 10 resulted in approximately two-fold higher frequencies of spike-positive cells compared with Jcovden at the same MOIs." (PMID 41341596, 2025). "At this very early stage of virus expression, myeloid-derived CD16+ virion sequence differed from CD16-/CD14+ virions by >2%, demonstrating multiple myeloid-derived viruses during the earliest days of infection." (PMID 38412143, 2024). "An important use case for our ts SeV-Cas9 system is infection and editing of primary human CD14+ monocytes, with the aim of inhibiting HIV infection." (PMID 39494910, 2024). "In the CNS, CD14+CD16+ monocytes contribute to infection and activation of parenchymal cells, resulting in production of neurotoxic viral and host factors that cause neuronal damage." (PMID 39253970, 2024). "After 6 days of viral exposure, flow cytometry was used to determine CD4+ T cell and CD14+ cell infection frequency in the mixed cell cultures." (PMID 39872519, 2024). "Emerging biomarkers such as soluble CD14 subtype (sCD14-ST) have shown promise in diagnosing infections." (PMID 39125464, 2024). "We infected primary human CD14+ MDMs from three independent healthy human donors and allowed the infection to spread for 10 days before harvesting cells (uninfected, 89.6wt or 89.6Δvpr infected) and prepared them for single-cell gene expression analysis." (PMID 38951492, 2024). "This adds to the observations that this nanobody conjugate can target US28 for degradation in the experimental infection of CD14+ monocytes and fibroblasts." (PMID 39452693, 2024). "Our approach is based on the detection in isolated hemocytes from G. mellonella hemolymph of cell membrane markers typically expressed by human immune cells upon inflammation and infection, for instance CD14, CD44, CD80, CD163 and CD200." (PMID 38191588, 2024). "Cell membrane markers typically expressed on monocytes/macrophages upon inflammation/infection (CD14, CD44, CD200), M1-polarization (CD80) and M2-polarization (CD163) were analyzed in the hemocyte population isolated." (PMID 38191588, 2024). "It is established that CD14 is expressed on the cells directly involved in combating infection, such as monocytes, macrophages, and neutrophils." (PMID 39202194, 2024). "Lentiviral vectors: Unfortunately, the infection of CD14+ monocytes with retroviral vectors similarly resulted in the generation of reprogrammed colonies but which did not establish as cell lines." (PMID 38891103, 2024). "The levels of surviving HCMV-infected CD14+ cells were assessed by the formation of foci of infection in fibroblast co-cultures." (PMID 39452693, 2024). "Fc receptors (FcαR, FcyR), Toll-like receptor TLR2 and cell surface receptor and differentiation marker CD14 were exclusively overproduced in the presence of hSAA-1 and downregulated (FcyR, TLR2, TLR4, CD14) during infection." (PMID 37781389, 2023). "After infection for 6 h, myeloid cells such as CD14− PMNs (mye-3, mye-6) and activated inflammatory MHC-II+Ly-6C+ Mφs (mye-10) were dominant in the lung." (PMID 37705063, 2023). "Consistently, we found that the frequency of intermediate monocytes (CD14+CD16+) increased during infection." (PMID 37033979, 2023). "To better understand the biological pathways modulated by the infection in B, CD14+, CD4+ and CD8+ cells, we next performed an over-representation analysis (ORA) using the Kyoto Encyclopedia of Genes and Genomes (KEGG)." (PMID 37920474, 2023). "PBMCs after Alpha strain infection showed the strongest CD14 and CD16 monocyte communication among the four strains." (PMID 38020713, 2023). "CD163 was expressed on some Mo and downregulated upon infection with the Velogenic strain as was the expression of CD14." (PMID 36680295, 2023). "It was observed that the percent expression of CD14 was increased in infection and decreased in the presence of TAK-242 (1μM) [from 5.57 ± 0.13% (mock) to 27.9 ± 2.088% (CHIKV) and 10.24 ± 1.157% (TAK-242)]." (PMID 37153546, 2023).
infection (continued). "These immune molecules are mainly associated with the recruitment of monocytes/macrophages, in keeping with the observation that animals had a higher frequency of macrophages (CD14+ CD68+) in peripheral blood three weeks post-infection with MTB." (PMID 37261336, 2023). "CD14+ neutrophils, which mainly increased in number during the recovery stage of infection, were revealed to have a stronger ability to produce cytokines, especially IL-10 and IL-21, than their CD14− counterparts." (PMID 37705063, 2023). "Representative MFI of FAM-FLICA+ CD4+, CD8+, CD11c+, and CD14+ splenic cells in one HIV-1 infected huNSG mice treated with vehicle or with VX-765-treated mice at day 22 post-infection is shown." (PMID 36800238, 2023). "The levels of PMNs highly expressing CD14 started to increase post-12 h infection and reached the highest level at 24 h after infection." (PMID 37705063, 2023). "CD14+ monocytes were isolated and differentiated into monocyte-derived macrophages (MDMs) before infection with L4 or L5 endemic strains." (PMID 37645380, 2023). "We found that upon infection, there is an expansion of all the myeloid cells, but notably so within the Mrc1+ macrophage, Cd14+ monocyte and Cd207+ Langerhans cell subclusters." (PMID 37644007, 2023). "Previous single-cell sequencing of blood samples from SFTSV patients revealed a phenotypic shift in monocyte populations from classical (CD14+CD16−) to intermediate (CD14+CD16+) following SFTSV infection." (PMID 37033979, 2023). "Our results confirm that an increase in CTSG mRNA expression correlates with higher levels of CTSG protein expression in the supernatants of MAP-infected CD14+-MDMs obtained from cows with the AC genotype following 2 h of infection." (PMID 36359162, 2022). "Latent infection of CD14+ monocytes provides a useful model to address questions surrounding the effects of viral gene products on driving differentiation from monocytes to macrophages or dendritic cells." (PMID 35012351, 2022). "The role played by CD14 in host defence mechanisms is always protective through activation of an immune response, whereas the level of CD14 expression in MΦs during infection depends on the type of the virus and bacterium." (PMID 35203475, 2022). "Cd14 was expressed by the epithelium, endothelium, and monocytes/macrophages before OM, with the endothelium and PMNs added after infection." (PMID 36092940, 2022). "Other myeloid cell types such as Cd14+ monocytes and Mrc1+ BAMs constitute additional responders to the infection, albeit with opposing effects; Cd14+ monocytes and Mrc1+ BAMs display pro- and anti-inflammatory phenotypes, respectively." (PMID 36180478, 2022). "This analysis identified a signature for 4 genes, CEBPD (0.93 log2FC), MAFB (0.83 log2FC), IFITM3 (0.55 log2FC), and LGALS1 (−0.53 log2FC), that was markedly enriched in CD14 monocytes in patients who ultimately survived infection." (PMID 35169146, 2022). "Infection with either attenuated NH/P68 or virulent 26544/OG10 resulted in the downregulation of both CD14 and CD16 expression, with a stronger intensity in infected (p72+) compared to bystander (p72−) moMΦ." (PMID 35215110, 2022). "IRF2 in combination with CD14 best distinguishes the Ly6Chi population in the ameba and listeria model from the population in naïve mice at least on day 3 post infection, the peak of liver pathology in these models." (PMID 36010615, 2022). "CD14 downregulation was evident in all the subsets, even though the expression of this marker had already been reduced before infection by the action of IL-10 or TGF-β." (PMID 35215110, 2022). "For CD14, we detected an increase of the percentage of cells expressing this marker, especially upon shB2 transduction, at 72 h post infection." (PMID 34862459, 2022).
infection (continued). "CD14+ monocytes have only a short half-life in circulation (1 to 3 days); however, direct infection of monocytes with HCMV has been shown to prolong the life of the cells by induction of specific antiapoptotic and proautophagic signaling." (PMID 35012351, 2022). "Cows with the AC genotype have significantly higher CTSG protein levels (1.85 ng/mL) in the supernatants of enriched CD14+-MDMs after 2 h of infection when compared with infected CD14+-MDMs from cows with the AA genotype (1.68 ng/mL)." (PMID 36359162, 2022). "As CD14+ monocytes can be easily isolated from venous blood, direct infection of these cells has been used to develop a model of latent HCMV infection." (PMID 35012351, 2022). "The co-receptor for TLR 4, CD14, is not present on platelets, but their response to a TLR 4-driven stimulus is potentiated in the presence of soluble CD14, an acute phase reactant increased in the presence of infection and inflammation." (PMID 34711945, 2022). "Total monocyte population (CD14+) increased after the secondary infection in accordance with an increase in intermediate (CD14+CD16+), and non-classical (CD14dimCD16+) subpopulations." (PMID 35743356, 2022). "In particular, genes that are known to activate NF-kappaB, e.g., TLR1, TLR3, TRAF5 and CD14, showed increased expression over infection time." (PMID 36544767, 2022). "Infection of PMA-treated THP-1 cells with MAP showed that the CD14+ cluster (classically differentiated macrophages) was most responsive to MAP, and this response was suggested to be associated with significantly higher TLR2 expression in that cluster." (PMID 34214113, 2021). "The results showed that phenotypical maturation and cytokine production of cDC2 or CD14+ DCs were evident only when the infection reached at a higher level, > 39.6 ± 0.8%, where the cell viability dropped significantly." (PMID 34177915, 2021). "The authors found that plasma levels of CD235a+ and CD14+ exosomes were significantly increased in patients with moderate infection, whereas CD8+ and CD19+ exosomes were decreased compared with the group of healthy subjects." (PMID 34440265, 2021). "Tracking of vesicles 1 h after infection with C. albicans by staining for CD14 and nucleic acids revealed that nucleic acid-containing vesicles accumulated around the cell nucleus as well as extracellularly." (PMID 35132877, 2021). "Few changes in myeloid cell proportions were observed following ZIKV-infection, although CD14+ CD163– CD206– cells were higher in the decidua of uninfected macaques compared to ZIKV-infected macaques (22.0 ± 13.1% and 8.5 ± 6.4%, respectively, p = 0.025)." (PMID 34394129, 2021). "Within the myeloid APC population, we also analyzed the levels of infection in CD14+ monocytes and CD1c+ DCs, and we found a significant detection of infected cells in the population of CD14+ monocytes at 24 hpi." (PMID 34160241, 2021). "CSFV infection led to the emergence of an additional CD163+CD14+ cell population, which showed the highest levels of Alfort-187 and C-strain infection." (PMID 34445493, 2021). "Chromatin accessibility for pro-inflammatory and infection-associated genes such as Il1b, Il6, Nlrp3, Itgam (Cd11b), CD80, CD14, Fos, and Jun were also increased in infected AMs and IMs (cluster 5)." (PMID 34292313, 2021). "In particular, plasma levels of CD235a+ and CD14+ EVs in patients with moderate infections significantly increased." (PMID 33925492, 2021). "More precisely, our data show that the circulating CD14+ CD16+ monocyte fraction increases at these time points probably because of the infection." (PMID 34594325, 2021). "Plasma levels of CD235a+ and CD14+ EVs in patients with moderate infection were significantly increased while CD8+ and CD19+ EVs were decreased comparing with HD." (PMID 33925492, 2021).
infection (continued). "MDSCs are a heterogeneous population of cells which expand during cancer, inflammation and infection, with a remarkable ability to suppress T-cell responses, and were defined as CD11b+ CD14- CD33+ in most tumors." (PMID 35069553, 2021). "We found expression of HLA-DPB1, a MHC class II gene, in CD14+ monocytes was inversely correlated with severity of infection, whereas expression of alarmins (e.g., S100A9) in CD14+ monocytes was positively correlated with severity." (PMID 33765435, 2021). "Plasma levels of CD235a+ and CD14+ EVs in patients with moderate infections significantly increased, while CD8+ and CD19+ EVs decreased compared with HD." (PMID 33925492, 2021). "The production of CXCL10 and CCL8 by latently infected monocytes was confirmed by ELISA; the level of both chemokines in the latently infected CD14+ monocytes were significantly increased over mock and UV inactivated infection controls." (PMID 33912186, 2021). "For DC subsets, we observed significant increases in myeloid DCs (CD14-CD11b+CD11c+) and unspecified DCs (CD14-CD11b+CD11c-) in blood, spleen, and bone marrow at 7 days post-infection." (PMID 34106915, 2021). "First, infection with the low-virulence Nc-Spain1H isolate induced an early increase in circulating CD14+ cells." (PMID 34239816, 2021). "At 25 days post-infection, we observed a decrease in myeloid DCs and unspecified DCs in the blood, and a decrease in monocyte-derived DCs (CD14-CD11b-CD11c+), myeloid DCs, and unspecified DCs in the spleen." (PMID 34106915, 2021). "Flow cytometry analysis revealed increased CD14 expression upon lenti-shHMGB1 infection relative to lenti-ctrl infection." (PMID 33128580, 2021). "The CD38+/CD14+ cells were the main cell population that expressed high levels of ABCA1 after infection." (PMID 32544188, 2020). "In turn, infection by both strains provoked upregulation of cell surface expression of the lipopolysaccharide (LPS) receptor CD14 and of the HLA-DR molecule involved in antigen presentation to T cells." (PMID 33293402, 2020). "Transcriptome group 1 (CAMP, CD14, FN1, TREM1) encodes for proteins that relate to acute response to infection, in particular to the LPS/TLR4 signaling pathway." (PMID 32325790, 2020). "We used the Massively Parallel RNA Sequencing (MARS-seq) platform to analyze experimentally infected primary CD14+ monocytes at different days post infection (dpi)." (PMID 31967545, 2020). "Following tissue damage and infection, classical monocytes, defined as CD14+ cells in humans, and Ly6C+ cells in mice critically contribute to inflammatory reactions by promoting and resolving acute challenges." (PMID 31916932, 2020). "In the current study, we did not detect any differences between Silirum vaccinates and non-vaccinates when analyzing the frequency of T cells (CD4+, CD8+, γδ+), ILCs (CD335+), or myeloid cells (CD14+ or CD11c+) in PBMCs at 28 days post-infection." (PMID 33329565, 2020). "Longitudinal phenotypic analyses revealed sustained significant changes in the composition of monocytes following infection, with increased CD14+CD16− and decreased CD14−CD16+ subsets." (PMID 32566226, 2020). "CD14+ cells were isolated pre-infection (baseline), on day 9 after infection, day 36, and 7 months after infection, and treated with different stimuli." (PMID 33324683, 2020). "Analysis of IL-10 and TNF-alpha expression showed that both cytokines were upregulated after infection in CD14+ and CD14- cells." (PMID 33146244, 2020). "In our study, we observed altered expression of LPB (FC-2.0) and CD14 (FC-1.7) which reflects activation of the host immune response against infection." (PMID 32518370, 2020). "CD14 release has been described during infection due to proteinase-dependent shedding; however, there is also a proteinase-independent CD14 release that is less well understood." (PMID 33135636, 2020).
infection (continued). "CD14 gene is a major part of the innate immune system, and one of essential receptors needed to initiate an adequate response to infection." (PMID 31963925, 2020). "Isolated brain CD45-positive cells revealed a significant population of resident CD14-positive cells, which was considerably decreased 8 days post-infection." (PMID 33072626, 2020). "On the other hand, P strain-infected macrophages showed the highest percentage of CD14+ HLA-DR++ cells revealing a differential expression pattern after infection with C#1 or P strain." (PMID 31695702, 2019). "Although neutrophil counts decreased initially after first infection, the frequency of CD14 expressing cells among them increased after first as well as after second infection." (PMID 31539406, 2019). "Flow cytometry analysisshowed that the frequency of mdDCs(CD11c+/CD14-/CD209+) infected(4G2+) with ZV BR 2015/15261 (25.54% ± 21.12) was similar to thefrequency of infection with ZIKV PE243 (27.47% ± 16.98) and ZIKV MR766 (24.84% ±20.49)." (PMID 31432892, 2019). "In acute inflammatory conditions such as infection or trauma, Ly6Chi monocytes, which are the mouse counterparts of human CD14+ classical monocytes, are recruited to the site of inflammation via CCL2-CCR2 interactions." (PMID 31888754, 2019). "Presepsin (P-SEP), the newly identified infection biomarker, is a 13 kDa fragment of the N-terminal of soluble CD14 and is released into the blood upon the activation of monocytes in response to infection." (PMID 31016020, 2019). "Following infection, CD14 is phagocytized with pathogens and cleaved, with subsequently soluble CD14 subtype (presepsin) being generated and released." (PMID 31226876, 2019). "Depletion of CD14+ monocytes from peripheral blood resulted in a reduction of these markers and reduced priming of NK cells during infection." (PMID 29600283, 2018). "SIV+ animals had high levels of circulating CD14+/CD16+ monocytes 28 days after infection and ~300 cells/μL by 8 wpi." (PMID 29750804, 2018). "Latent infection occurs in less differentiated CD34+ hematopoietic progenitor cells (HPCs) in the bone marrow as well as CD14+ monocytes." (PMID 30360396, 2018). "For the CD14, a decreasing trend was observed during the early stage, which was statistically significant at the chronic stage of the infection." (PMID 30547823, 2018). "Regarding the dynamics of APC, a different tendency was observed during the early stage of infection for CD14, MHCII and CD83 cells." (PMID 30547823, 2018). "In accordance, CD14+ cells strongly upregulated CD86 during infection with HTNV and high levels of soluble CD86 were detected in hantavirus-infected patients." (PMID 30559738, 2018). "The observed antibody-dependent enhancement (ADE) of infections in CD14+ was consistent with previous reports of in vitro infection in human PBMC with wild-type dengue viruses." (PMID 29547653, 2018). "HIV was still detected in CD14+ cervical cells 5 days post-infection, but now was also detected in CD4 T cells." (PMID 30532754, 2018). "The known recognition of TLR2/CD14 N-glycans on innate immune cells by ArtinM is essential for inducing Th1 cytokine production, which favors the host immune response against infection by intracellular pathogens." (PMID 30216978, 2018). "CD14 has regulatory function in infection and damage, a necessary requirement for immune cells in inflamed tissue." (PMID 30519676, 2018). "For example, AF and AS ZIKV strains produce different immunoprofiles in human CD14+ monocytes following blood infection." (PMID 29985932, 2018). "Based on antibody availability, we selected five proteins (FCGR3, FCGR1, CD274, ICAM1, SLAMF8) to profile 24 h after infection with pseudotyped HIV-1 by flow cytometry in CD14- CD11cHi HLADR+ DCs from our cultures." (PMID 29378643, 2018). "One of the most noteworthy findings of our study was the influence of the infection on peritoneal CD14, CD83 and MHCII cells over time." (PMID 30547823, 2018).